ALB (albumin)
Diseases named in the same sentence as ALB in open-access papers (continued):
Sharing a sentence is not in itself a finding about the gene and the disease.
heart failure (continued). "The serum albumin creatinine ratio (sACR) has been established as a potential indicator for heart disease, however, its relationship with prognosis in intensive care unit (ICU) patients with heart failure remains uncertain." (PMID 39027002, 2024). "1se (λ = 0.005), the candidate predictors of the initial screening include the following 15 variables: age, height, albumin, creatinine, chloride, AST, race, pneumonia, AKI, COPD, myocardial infarction, cardiac dysrhythmia, heart failure, heparin, and antibiotic treatment." (PMID 38007467, 2023). "Albumin urination is the warning signal of renal engagement over exertion and most frequently heralds heart failure development, regardless of disease etiology." (PMID 37373108, 2023). "In line with this, higher rates of heart-failure-related hospitalization and cardiovascular death were demonstrated in patients with low albumin irrespective of severity and subtype of AMI in 2253 AMI patients during a median follow-up of 3.2 years." (PMID 37108536, 2023). "Actually, both BMI and serum albumin levels (which are components of the GNRI) may fluctuate due to systemic status, time elapsed since the onset of AMI, and accompanying heart failure." (PMID 38004141, 2023). "In myocytes from mice with heart failure or with a sodium channel mutation but not in healthy murine cardiac myocytes, 1 EMPA, in the absence of albumin, reduced late-INa in cardiomyocytes." (PMID 35303888, 2022). "Conventional treatment for heart failure could attenuate the changes in up- (CPN1, and C3) and down-regulated proteins (serum albumin precursor, albumin isoform X1, IGLC, and fetuin-B) in stage C CHF." (PMID 35203200, 2022). "Except for age, HCC status, and MELD score, there were no statistical difference between the two groups for sex, HE grade, ascites amount, EV grade, EVB, SBP, HRS, DM, ESRD, heart failure, serum ammonia, INR, WBC, Hb, PLT, creatinine, bilirubin total, AST/ALT, or albumin." (PMID 34071787, 2021). "In Model 3, after adjusting for age, BMI, number of drugs, CCI, heart failure, RBC, albumin, total cholesterol, triglyceride, LDL-C and HDL-C, lower RDW (β = −0.721, P = 0.033) was a protective factor for frailty, while lower HRR (β =1.126, P = 0.004) was a risk factor for frailty." (PMID 34513961, 2021). "Therefore, in this study, angiotensin II (AT1) peptide conjugated human serum albumin nanoparticles (AT1-HSA-MRN-NPs) have been synthesized for targeted delivery of MRN to the myocardium, overexpressing AT1 receptors under heart failure." (PMID 34591850, 2021). "There was a significant positive correlation of albumin with pIgR peptides levels (rho = 0.277; p = 0.005) in the heart failure and CAD patients without CKD." (PMID 32427855, 2020). "Our cluster analysis suggests that immunological parameters (helper T lymphocyte count and cytotoxic T lymphocyte count) and serum albumin level are important in determining prognosis and the vulnerability to developing comorbidities, including respiratory failure, ARDS, and heart failure." (PMID 33282887, 2020). "There were significant correlations between urine albumin values and cardiovascular disease and angina but not with ischemic stroke, myocardial infarction and cardiac failure." (PMID 19609391, 2008). "The NPAR, which combines neutrophil percentage and albumin, is a prognostic factor for patients suffering from various chronic non-communicable diseases such as heart failure, chronic obstructive pulmonary disease, metabolic syndrome, and non-alcoholic fatty liver disease." (PMID 40860482, 2025). "The longer length of stay observed in the heart failure cohort might not be directly related to albumin administration, as the length of stay is influenced by various complex clinical factors." (PMID 40279952, 2025).
heart failure (continued). "The platelet-albumin-bilirubin (PALBI) score has shown prognostic value across multiple medical conditions; nevertheless, its effectiveness in forecasting prognoses among severely ill heart failure (HF) patients treated in Intensive Care Unit (ICU) has yet to be fully established." (PMID 41210328, 2025). "The model was adjusted for heart failure, history of myocardial infarction and neoplasm, number of chronic diseases, MNA-SF score, serum protein concentration (<6/dL), hemoglobin level, NT-proBNP, GFR, serum albumin, low physical activity, GDS-15 score, Short-Blessed test score, and sex." (PMID 41228486, 2025). "The groups differed from each other on several baseline parameters, including age, smoking, hemoglobin, albumin, CRP, creatinine, leukocytes, oxygen supply, peripheral oxygen saturation (pulse oximetry), body temperature, respiratory frequency, and prevalence of heart failure and COPD." (PMID 40271386, 2025). "The high albumin and total protein concentrations indicate no acute inflammation and possibly a state of contraction of blood volume, which is often seen in patients treated with diuretics for heart failure or other cardiovascular conditions." (PMID 38200252, 2024). "In the acute phase of AMI, however, BMI, serum albumin levels, and total lymphocyte counts, which are key components of the GNRI, CONUT, and PNI, may fluctuate due to systemic status, time elapsed since the onset of AMI and accompanying heart failure." (PMID 38004141, 2023). "Meanwhile, the BMI, RBC counts, hemoglobin, albumin and left ventricular ejection fraction (LVEF) showed significantly negative correlation with HAM-D24 score in hospitalized heart failure patients." (PMID 27955661, 2016). "Statistically significant differences were found between the group that included readmitted patients and the group who were not readmitted regarding albumin concentration, presence of white nails, time to readmission, home discharge, CCI, heart failure, peptic ulcer, DM, COPD, cancer, and dementia." (PMID 35602847, 2022).
kidney damage (417 papers, 2005 to 2026). "Meanwhile, a correlation between either total T lymphocytes or helper T lymphocytes and serum albumin was detected on patients with nephropathy due to other causes." (PMID 40277801, 2025). "An elevated loss of protein/albumin in urine is a marker of kidney damage; moreover, albuminuria has a direct toxic effect on the renal tubules." (PMID 37189791, 2023). "Mice of both strains exhibited terminal urinary retention and severe kidney damage with elevated urinary albumin levels, loss of nephrons, renal fibrosis, presence of storage vacuoles, and dysmorphic mitochondria in the intraglomerular and tubular cells." (PMID 37698928, 2023). "Increased albumin concentration in the urine is associated with kidney damage and renal injury, with normalisation to creatinine (consistently released)." (PMID 36260752, 2022). "Traditionally, the initial diagnostic sign of DN is albuminuria, with urinary albumin of 30–299 mg/g creatinine indicative of early nephropathy, and more than 300 mg/g creatinine signifying overt nephropathy." (PMID 35334601, 2022). "Other studies have shown that the levels of this substance increase with the development of nephropathy and are independently associated with urinary albumin excretion." (PMID 34307650, 2021). "In some studies, the renal outcome (such as the albumin excretion rate, nephropathy presentation rate, risk for ESRD) was significantly higher among subjects with either PDR or severe NPDR relative to mild NPDR." (PMID 33374974, 2020). "In the present study, use of hyper-oncotic albumin solution was associated with kidney damage, according to AKI score and molecular markers of kidney dysfunction." (PMID 31311539, 2019). "An upregulation of KIM-1 in lipid-overloaded proximal tubules further supports a pathogenic role of albumin-conjugated FAs in tubular injury and nephropathy progression." (PMID 31373312, 2019). "Recommendations for evaluating people at increased risk are to measure urine albumin to assess kidney damage and to estimate the GFR with an equation based on the level of SCr." (PMID 28118757, 2017). "Microalbuminuria is commonly used as an indicator of early kidney damage, and the detection of increased albumin and/or total protein excretion is associated with poorer renal and cardiovascular prognosis." (PMID 23446441, 2013). "Inflammation is a suspected cause of kidney damage; and we were interested in testing associations of genes involved in the inflammatory response with urinary albumin excretion." (PMID 21054877, 2010). "Several factors can contribute to the decreased serum total protein, globulin, and albumin, levels in Cd and/or TNP-induced kidney damage like proteinuria and concomitant loss of albumin and other proteins from the bloodstream, leading to decreased serum total protein, albumin, and globulin levels." (PMID 39707081, 2025). "The decrease in total protein and albumin levels could be attributed to impaired liver function and protein loss due to kidney damage; or due to insufficient take of protein in diet and diarrhea." (PMID 39316350, 2024). "Hence, administering treatment based on intravenous albumin and antibiotics improves survival and reduces the risk of kidney damage." (PMID 39337069, 2024). "Furthermore, stearidonate was significantly associated with increased urinary albumin excretion which indicates nephropathy and reflects endothelial dysfunction and kidney damage in the metabolomic analysis of patients with albuminuria." (PMID 38390445, 2024). "Serum ALB is the main carrier protein for protein-bound gut-derived uremic toxins (PBUTs), making the toxin molecules difficult to clear from the body and cause kidney damage." (PMID 38819146, 2024). "Thus, elevated urinary ALB is a reliable diagnostic indicator for the early detection of nephropathy." (PMID 37624173, 2023).
kidney damage (continued). "Although serum albumin level is not specific to nutritional status and systemic inflammation or nephropathy were strongly associated with low serum albumin levels, optimal nutritional engagement to maintain serum albumin levels is indispensable in addition to CLTI management." (PMID 35574536, 2022). "An opposite trend was observed in the concentrations of albumin, being lower at the pre-treatment sample collection probably as a consequence of protein-losing nephropathy with glomerular leakage of proteins caused by the damage of renal cells by inflammatory mediators in the affected dogs." (PMID 35327106, 2022). "A damaged glomerulus due to nephropathy may cause greater dissociation of the copper/albumin and copper/ceruloplasmin complexes, and urinary copper overload may, in turn, play an important role in the progression of nephropathy." (PMID 36676942, 2022). "Abnormal urine albumin excretion is a hallmark for incipient nephropathy." (PMID 34963468, 2021). "However, it has been demonstrated that albumin suffers different posttranslational modifications, including oxidation, which appears to be tightly linked to kidney damage progression and is increased in obese patients." (PMID 33800425, 2021). "Moreover, previous reports have demonstrated that the oxidized form of albumin is associated with the pathophysiology of various diseases, including nephropathy and dyslipidemia." (PMID 33578917, 2021). "Previous reports have also suggested that albumin oxidized at the Cys34 residue may be associated with diseases such as nephropathy and dyslipidemia." (PMID 33578917, 2021). "Furthermore, the nephropathy diagnostic method used here, a random urine dip-stick, is potentially less sensitive than the recommended method of albumin to creatinine measurement of first morning urine samples or kidney biopsy." (PMID 32346524, 2020). "Different markers of kidney damage like proteinuria and albumin excretion might be associated with both AF and renal dysfunction." (PMID 30395598, 2018). "Therefore, our current study demonstrated a crosstalk between albumin overload/ER stress/podocyte apoptosis and identified new targets for the prevention of podocyte injury in nephropathies associated with albuminuria." (PMID 30573754, 2018). "It was shown that regardless of exposure to nephrotoxic chemicals, the urinary albumin levels were high depending on shift worker groups, suggesting that the disruption of circadian rhythm may cause kidney damage." (PMID 30564370, 2018). "Furthermore, serum albumin is difficult to interpret in the context of nephropathy due to albumin urinary loss." (PMID 27248151, 2016). "Recent studies have shown that concentrations of these substances increase as nephropathy progresses and that these inflammatory molecules are independently related to urinary albumin excretion (UAE) presenting a direct association with clinical markers of glomerular and tubulointerstitial damage." (PMID 25785280, 2015). "Besides assessing the diagnostic accuracy of the one testing UACR for detection of microalbuminuria, we test diagnostic performance of one estimating urine albumin level and also urine creatinine level for assessment of kidney damage." (PMID 24455207, 2013). "Furthermore, DM is characterized bychronic hyperglycemia, which not only correlates with adverse prognosis in ACSpatients but also causes long-term complications like nephropathy, which coulddecrease serum albumin levels." (PMID 40351679, 2025). "An admixture mapping study of albuminuria-increased albumin excretion, which is a sign of kidney damage-performed on ~12,000 admixed individuals with sociodemographic assessment, identified two signals enriched in Indigenous ancestries associated with increased urine albumin excretion." (PMID 39254840, 2024).
kidney damage (continued). "The hypothesis suggests that constant urinary albumin loss stimulates compensatory synthesis of large amounts of lipoproteins in the liver leading to hyperlipidemia and lipid-mediated kidney damage, thereby aggravating the progression of glomerular and tubulointerstitial diseases." (PMID 34485530, 2021). "Compared to iso-oncotic albumin, hyperoncotic albumin leads to a higher osmotic pressure, which may alter intraglomerular oncotic force and osmotic nephrosis, and is associated with worse kidney damage." (PMID 33317590, 2020). "The decrease in the level of TOP and ALB in fish infected with R. salmoninarum could be explained by a reduction in protein synthesis due to liver damage and by the higher excretion of protein or protein loss associated with kidney damage." (PMID 32695119, 2020). "It is well established that the urinary albumin level is a sensitive marker of glomerular injury and the fact that the cigarette smoking is associated with albuminuria indicates a direct or indirect relationship of cigarette smoking in initiation and progression of kidney damage." (PMID 24465635, 2014). "Neuropathy was assessed using the 10 g monofilament test, retinopathy by fundus examination, and nephropathy by urine albumin-to-creatinine ratio (ACR)." (PMID 41873277, 2026). "Diabetic patients were categorized into four stages of nephropathy according to estimated glomerular filtration rate (eGFR) and urinary albumin-to-creatinine ratio (ACR) based on KDIGO criteria." (PMID 42099535, 2026). "Patients who received albumin showed longer intervals (18.2 ± 4.3) between procedures, as well as lower rates of both PICD (7 (11.7%)) and kidney damage (6 (10.0%)), which confirmed the therapeutic benefits of albumin." (PMID 40662011, 2025). "To check the presence and evidence of kidney damage in this model of 7 days, we evaluate albuminuria and albumin/creatinine ratio." (PMID 40362413, 2025). "When nephropathy due to other causes in end-stage CKD origin is considered, serum albumin concentration positively correlates with T lymphocytes and helper CD4+ T cells." (PMID 40277801, 2025). "Consistent with substrate accumulation and structural kidney damage, at baseline, G3Stg/GlaKO mice presented with a mild yet statistically significant increase in urinary albumin." (PMID 40149554, 2025). "ClC-5 overexpression in podocytes enhances albumin endocytosis, potentially compensating protein overload in nephropathies." (PMID 41009556, 2025). "The slow but progressive decline in renal function despite combined immunosuppressive therapy, along with the need for frequent intravenous albumin supplementation, illustrates the limited efficacy of conventional treatment in genetic forms of nephropathy." (PMID 41562995, 2025). "Dogs with membranous glomerulonephropathy had lower serum albumin concentrations (median, 2.1 g/dL) than dogs with glomerulosclerosis (median, 3.0 g/dL; p = 0.01) or other nephropathies (median, 3.0 g/dL; p = 0.04)." (PMID 40692207, 2025). "Compared to untreated diabetic rats in Image (Control—LA), rats treated with Lactobacillus acidophilus showed notably lower levels of albumin and glucose in urine samples, indicators of kidney damage in the present work." (PMID 40001890, 2025). "It was significantly increased in DM rats during the progression of diabetes and was better than urinary albumin excretion in predicting kidney damage in DM." (PMID 40308771, 2025). "The immunoassay and LA SP ICP MS readout were optimized usinghuman serum albumin, a kidney damage biomarker, as a model analyte,obtaining LODs of 0.18 and 0.12 ng/mL for the reference upconversionluminescence (UCL) and LA SP ICP MS readout, respectively." (PMID 40556296, 2025). "Conversely, HM exacerbateddiabetic nephropathy, elevating urinary albumin-creatinine ratio (411.90±88.86vs." (PMID 41161321, 2025).